FUT1 (fucosyltransferase 1 (H blood group))
Description:
Catalyzes the transfer of L-fucose, from a guanosine diphosphate-beta-L-fucose, to the terminal galactose residue of glycoconjugates through an alpha(1,2) linkage leading to H antigen synthesis that is an intermediate substrate in the synthesis of ABO blood group antigens. H antigen is essential for maturation of the glomerular layer of the main olfactory bulb, in cell migration and early cell-cell contacts during tumor associated angiogenesis. Preferentially fucosylates soluble lactose and to a lesser extent fucosylates glycolipids gangliosides GA1 and GM1a (By similarity).
Synonyms: H; HSC; HH
Tractability: Antibody: its Gene Ontology location is reachable by antibodies, with high confidence; UniProt predicts a signal peptide or a membrane-spanning region.
Gene: Protein-coding gene on chromosome 19 (48,748,011 to 48,755,390, reverse strand). Ensembl gene ENSG00000174951.
Subcellular location: Golgi apparatus, Golgi stack membrane
Pathways (Reactome):
Metabolism: ABO blood group biosynthesis; Glycosphingolipid biosynthesis
Gene Ontology:
Molecular function: alpha-(1,2)-fucosyltransferase activity; fucosyltransferase activity; galactoside 2-alpha-L-fucosyltransferase activity
Biological process: positive regulation of cell-matrix adhesion; positive regulation of endothelial cell migration; positive regulation of endothelial cell-matrix adhesion; positive regulation of sprouting angiogenesis; carbohydrate metabolic process; glycoprotein biosynthetic process; glycosphingolipid biosynthetic process; L-fucose catabolic process; olfactory bulb development; oligosaccharide biosynthetic process; protein O-linked glycosylation via fucose; carbohydrate derivative biosynthetic process; glycolipid metabolic process
Cellular component: Golgi apparatus; Golgi membrane; membrane; plasma membrane; Golgi cisterna membrane
Genetic constraint (gnomAD): Loss-of-function variants: 4 observed, 3.35 expected, observed/expected ratio (o/e) 1.19, 90% interval 0.55 to 1.89. That is too few expected variants to judge how well the gene tolerates losing a copy. Missense variants: 476 observed, 522.65 expected, observed/expected ratio (o/e) 0.91, 90% interval 0.84 to 0.98. Synonymous variants: 215 observed, 221.41 expected, observed/expected ratio (o/e) 0.97, 90% interval 0.87 to 1.09.
Homologues: Orthologues: chimpanzee FUT1 (99% identical), macaque FUT1 (95% identical), rabbit FUT1 (81% identical), pig FUT1 (81% identical), mouse Fut1 (78% identical), rat Fut1 (76% identical), guinea pig FUT1 (75% identical), tropical clawed frog fut1 (52% identical), tropical clawed frog fut2 (47% identical), Caenorhabditis elegans B0205.4 (21% identical). Paralogues in human: FUT2 (56% identical).
Diseases named in the same sentence as FUT1 in open-access papers:
FUT1 is named in the same sentence as 113 diseases in open-access papers, as found by Europe PMC text mining. Sharing a sentence is not in itself a finding about the gene and the disease. The quoted sentences say what the papers report.
breast carcinoma (15 papers, 2013 to 2024). "Firstly, meta-analysis of breast cancer data shows that high levels of expression of FUT1 and FUT3 are associated with a bad prognosis." (PMID 26908442, 2016). "In this study, we revealed that the rBC2LCN‐positive cell lines exhibited higher FUT1 expression compared with that in the rBC2LCN‐negative cell lines, indicating that rBC2LCN can detect breast carcinoma cells with high FUT1 expression." (PMID 32237061, 2020). "Fucosyltransferase 1 (FUT1) was suggested to play important roles in the growth regulation, adhesion, migration, and cancer stem cell properties of human breast carcinoma cells in vitro." (PMID 32237061, 2020). "B3GALT5 and FUT1/FUT2 have been known to be involved in the biosynthesis of Globo H in breast carcinoma cell lines." (PMID 32237061, 2020). "Here, we investigated the impacts of alpha 1, 2-linked fucose on breast cancer biology and CSC properties using lentiviral system to knockdown and electroporation to overexpress FUT1 and FUT2.." (PMID 30854233, 2019). "Analysis of the transcriptome of the 51 breast cancer cell lines showed an inverse relationship between expression of FUT1/3 and of SNAI2 and ZEB1/2." (PMID 26908442, 2016). "Among these, AXL and FUT1 were previously determined as the targets of miR-34a in non-small cell lung cancer, colorectal cancer and breast cancer." (PMID 25762634, 2015). "In breast cancer, FUT1 and FUT2 have been involved in regulating growth, adhesion, and migration of breast cancer and might serve as a therapeutic target." (PMID 38670309, 2024). "From these findings, we hypothesized that rBC2LCN has the potential to detect breast carcinoma cells that acquire aggressiveness secondary to high FUT1 expression in breast carcinoma tissue." (PMID 32237061, 2020). "For example, increased expression of FUT1 has been associated with increased propensity to metastasize in melanoma and advanced stage in ovarian cancer, while downregulation of FUT1 in a HER2-positive breast cancer cell line decreased proliferation." (PMID 28031957, 2016). "Elevation of FUT1, GCNT2, and GCNT3 expression as seen in RWPE1 cells cultured under hypoxia may similarly underlie colon and breast cancer survival responses to hypoxia and promote invasion and metastasis." (PMID 24753248, 2014). "For example, FUT1 and FUT2 promote growth, adhesion, migration, and cancer stem cell (CSC) properties of breast cancer." (PMID 34745942, 2021). "The expression levels of FUT1, human epidermal growth factor receptor 2 (HER2), and epithelial marker genes were higher in rBC2LCN‐positive than in rBC2LCN‐negative breast carcinoma cell lines." (PMID 32237061, 2020). "Glycan products of FUT1 and FUT2, such as Globo H and Lewis Y, are highly expressed on malignant tissues, including breast cancer." (PMID 30854233, 2019). "We have demonstrated the important roles of FUT1 and FUT2 in breast cancer as evidenced by their regulation of cell morphology, proliferation, adhesion, migration, and mammosphere formation in vitro and tumorigenicity and metastasis in vivo." (PMID 30854233, 2019). "Silencing of FUT1 or FUT2 suppressed cell migration in wound healing assay, whereas FUT1 and FUT2 overexpression increased cell migration and invasion in vitro and metastasis of breast cancer in vivo." (PMID 30854233, 2019). "Inhibition of cancer cell progression, angiogenesis and metastasis by FUT1 or FUT2 knockdown reduced expression of alpha 1, 2-fucosyl glycans has been found in many cancers including breast cancer." (PMID 30854233, 2019). "Suppression of FUT1 with reduced Ley expression inhibited epidermoid carcinoma (A431) and HER2-overexpressing breast cancer (NCI-N87) via EGFR19,26, and decreased adhesion of dendritic cells over endothelial cells via reduced Ley on ICAM-239." (PMID 30854233, 2019). "Upon silencing of FUT1 in MCF-7 and T47D breast cancer cells, we observed a striking change in the subcellular distribution patterns of LAMP-1 and 2 by immunofluorescence staining." (PMID 27560716, 2016).
breast carcinoma (continued). "Overexpression of FUT1 or FUT2 promotes the migration and invasion of tumor cells in breast cancer cell lines and metastasis in vivo, whereas FUT1 or FUT2 knockdown reduces Globo H and decreases mesenchymal-like markers, such as fibronectin, vimentin, and twist." (PMID 34948129, 2021). "Precedence for the role of FUT1 comes from the breast-cancer cell line T47D where FUT1 but not FUT2 controls the fucosylation of lysosomal proteins of LAMP1 and LAMP2 and lysosomal positioning." (PMID 34696500, 2021). "However, the roles of FUT1 and FUT2 in cancer stem cells (CSCs) and tumorigenicity of breast cancer have yet to be delineated." (PMID 30854233, 2019). "Herein, we investigated the roles of FUT1 and FUT2 in breast cancer." (PMID 30854233, 2019). "In addition, FUT1 and FUT2 are capable of generating FGM1 and Globo H in small cell lung cancer cells and breast cancer cells, respectively." (PMID 30854233, 2019). "Thus, this is the first report to provide evidence for the involvement of FUT1 in the topographical distribution of LAMP-1 and 2 that subsequently influences the autophagic activity and process of breast cancer cells." (PMID 27560716, 2016). "In conclusion, this study has provided the first evidence for a negative impact of FUT1 on autophagic flux in breast cancer cells through its influence on lysosomal positioning." (PMID 27560716, 2016). "Although LeY carried by surface LAMP-1 has been suggested to be involved in cell migration in breast cancer, no studies so far showing the correlation of FUT1-modified LAMP-1 and/or LAMP-2 with lysosomal localization and autophagic process." (PMID 27560716, 2016). "Furthermore, to determine whether FUT1 and FUT2 promote breast cancer metastasis in vivo, MDA-MB-231 stably and constitutively expressing luciferase by lentiviral-mediated gene transfer was transfected with empty vector, Flag-FUT1 or Flag-FUT2." (PMID 30854233, 2019). "Thus FUT1 and FUT2 may serve as good drug targets for breast cancer therapy." (PMID 30854233, 2019).
colon carcinoma (11 papers, 2010 to 2025). "FUT1 has been shown to be over-expressed in both human and rat colon cancers." (PMID 31365696, 2019). "For instance, FUT1 overexpression in HT-29/M3 colon cancer cells induces synthesis of H type 2 and Ley and decrease in sLex, which results in altered glycosylation patterns of MUC1 and MUC5AC apomucins with reduced interaction with E-selectin, leading to greater invasive and metastatic capacities." (PMID 30854233, 2019). "A numbers of recent studies have implicated important functions of FUT1 and FUT2 in colon cancers." (PMID 30854233, 2019). "Therefore, si-FUT1 inhibited cell migration and induced apoptosis in colon cancer cells." (PMID 35462848, 2022). "A previous study showed that FUT1 overexpression in colon cancer cells catalyzed the addition of α1,2-fucose to MUC5AC, indicating the implication of FUT1 in the glycosylation of MUC5AC26." (PMID 32332708, 2020). "Thus, the overexpression of FUT1, which competes for the same substrate as ST3Gal III and IV, showed a decrease in the metastatic potential of pancreatic adenocarcinoma and colon cancer cells after injection into nude mice." (PMID 20824144, 2010).
ovarian carcinoma (10 papers, 1998 to 2025). A malignant neoplasm originating from the surface ovarian epithelium. "For instance, transfection of the ovarian cancer cell line RMG-1 with a cDNA encoding the human Fut1 gene results in a high cell surface expression of the di-fucosylated Lewisy epitope and in a more aggressive phenotype." (PMID 29527514, 2018). "Moreover, FUT1 is involved in the proliferation of breast cancer cells and the development of paclitaxel resistance in ovarian cancer cells." (PMID 40084262, 2025). "We previously identified DEGs after transfection of FUT1 gene in ovarian cancer CAOV3 cell line, and found that the endoplasmic ERS-related gene HSPA8 was significantly changed, indicating that Lewis y may be involved in the ERS process." (PMID 36544104, 2022). "The combination of c-jun and the promoter of FUT1 induce the proliferation of ovarian cancer cells and the complexity of Lewis y/ FUT1 might be regulated by TGF-β1." (PMID 31639019, 2019). "In order to further investigate the effects of Lewis y antigen on CD147-regulated autophagy of ovarian cancer cells, we transfected CAOV3 cells with FUT1; the resulting cells are referred to as CAOV3-FUT1 cells (CA-FUT1)." (PMID 27863372, 2016). "However, in ovarian cancer (OV) (ρ=0.85, p=0.00342) and PCPG (ρ=0.35, p=1.25e-06), DNA promoter methylation levels were positively correlated with FUT1 mRNA expression." (PMID 40084262, 2025). "Interestingly, in vitro experiments also suggested that TGF-β1 dose-dependently induced terminal fucosylation via increased expression of FUT1, which is consistent with previous study showing FUT1 expression in response to TGF-β1 in ovarian cancer." (PMID 37085770, 2023).
melanoma (9 papers, 2015 to 2026). A malignant, usually aggressive tumor composed of atypical, neoplastic melanocytes. "Notably, miRNAs upregulating FUT1 are depleted in various cancers, aligning with observations that loss of α-1,2-fucosylation is a hallmark of esophageal cancer, melanoma biogenesis, and metastasis." (PMID 42225237, 2026). "One of the first pieces of evidence that fucosyltransferases might be implicated in melanoma progression came from the finding that the expression levels of FUT1 and FUT4 mRNA are significantly higher in metastatic melanoma cell lines (A375, WM9, WM239) compared to primary melanoma cells (WM35)." (PMID 34440905, 2021). "The levels of FUT1 were further suppressed in metastatic melanoma when compared to primary melanoma." (PMID 29924834, 2018). "In line with the previous experiments, FUT1 overexpression also inhibited the Matrigel invasion activity of WM793, suggesting that α-1,2 fucosylation mediated by FUT1 is sufficient to inhibit invadopodium formation and melanoma invasion." (PMID 29924834, 2018). "The expression of FUT1, an α-1,2 fucosyltransferase, is remarkably down-regulated during melanoma progression, and the ectopic expression of FUT1 is sufficient to inhibit invadopodium formation and ECM degradation." (PMID 29924834, 2018). "FUT1 mRNA levels were downregulated in malignant melanoma when compared to benign nevi or normal skin from human patients." (PMID 29924834, 2018). "Agrawal and colleagues performed a systematic analysis of the melanoma glycome of clinical samples and found upregulation of core fucosylation (FUT8) and downregulation of α-1,2 fucosylation (FUT1, FUT2) as features of metastatic melanoma." (PMID 34440905, 2021). "Fucosyltransferase 1 and 2 (FUT1 and FUT2) are the fucosyltransferases responsible for the transfer of L-fucose to glycans via α-1,2 linkages and has been shown to be involved in inhibition of melanoma cell migration and adhesion." (PMID 29924834, 2018). "It is interesting to note that the expression of FUT1 and FUT2, the two α-1,2 fucosyltransferases, are suppressed during melanoma progression, and the levels of α-1,2 fucosylation are inversely correlated with the survival of melanoma patients." (PMID 29924834, 2018).
colorectal cancer (8 papers, 2015 to 2025). A primary or metastatic malignant neoplasm that affects the colon or rectum. "Experimental validation confirmed that FUT1 knockdown inhibited proliferation, invasion, and migration in bladder, breast, and colorectal cancer cell lines, suggesting a potential role in cancer progression, though further evidence is required to fully establish its oncogenic involvement." (PMID 40084262, 2025). "As the downstream gene of the ceRNA interaction, FUT1 is controlled by ADP-dependent glucokinase antisense RNA 1 and miR-525 to affect colorectal cancer metastasis and malignancy." (PMID 38934781, 2024). "It has been proposed that fucosylation deficiency leads to colitis and adenocarcinoma in mice, while it remains unclear whether α-1,2 fucosylation (FUT1, FUT2) is relevant to colorectal cancer." (PMID 36973740, 2023).
bladder cancer (7 papers, 2016 to 2022). "Calreticulin has been shown to increase adhesion of bladder cancer cells by stabilizing mRNA for fucosyltransferase 1 (FUT-1), an enzyme responsible for α-1,2-linked fucosylation of β1 integrin." (PMID 36430846, 2022). "Terminal fucosylation of oligosaccharides mediated by FUT1 is correlated with bladder cancer progression." (PMID 34948129, 2021). "Modification of β1 integrin with α1,2 fucosylation can regulate cell adhesion and metastasis of bladder cancer cells when the expression levels of fut1 were upregulated." (PMID 32596162, 2020). "Fucosylation by FUT1 through α1-2 linkages promotes bladder cancer progression." (PMID 34948129, 2021). "Calreticulin can regulate the content of Fut1 in bladder cancer tissue." (PMID 32596162, 2020). "Interestingly, a recent study shows that overexpression of FUT1 in bladder cancer cell lines increases integrin ß1 activity and enhances cell adhesion." (PMID 26908442, 2016). "Interestingly, we previously showed that the overexpression of CRT enhanced the expression of RNA binding protein FUBP1, which binds to ARE in 3’ UTR of FUT1 mRNA, and therefore stabilized FUT1 mRNA in J82 bladder cancer cells to promote tumor formation and metastasis." (PMID 31725767, 2019). "In our previous study on bladder cancer, we showed that CRT was not part of the ARE binding protein complex and that it indirectly stabilized FUT1 mRNA degradation through activating the ARE binding protein FUBP1." (PMID 31725767, 2019).
epidermoid carcinoma (5 papers, 2014 to 2024). "In line with our findings, FUT1 knockdown has been shown to inhibit human epidermoid carcinoma cell proliferation, keratinocyte migration and synovial fibroblast proliferation." (PMID 36012728, 2022). "The EGFR in A431 cells, the squamous cell carcinoma cell lines, are glycosylated by A antigen, as well as Lewis Y antigen, another product of FUT1 that is mostly expressed in cancer cells, and these sugar structures influence the binding of the EGF to its binding site on the receptor." (PMID 39420441, 2024).
hepatocellular carcinoma (5 papers, 2017 to 2023). A malignant tumor that arises from hepatocytes. "For example, the overexpression FUT1 increased the α1,2-fucosylation, drove cancer stemness in hepatocellular carcinoma." (PMID 37798282, 2023). "In line, FUT1 and B3GALT5 appeared as promising genes associated with the GSLs investigated in this hepatocellular carcinoma study and were further suggested as specific targets for therapeutic intervention." (PMID 33418847, 2021). "Following an examination of the gene expression of their biosynthetic enzymes, FUT1, FUT2, B3GALT5, and ST3GAL2 in hepatocellular carcinoma tissue samples, using RT-qPCR, revealed an association of FUT1 or B3GALT5 expression with advanced stages." (PMID 33418847, 2021). "FUT1 overexpression is a poor prognostic indicator of hepatocellular carcinoma." (PMID 35462848, 2022). "A recent study showed that FUT1/2 induced angiogenesis by activating ERK1/2, accelerated hepatocellular carcinoma progression by influencing Notch signaling, and multidrug resistance by inducing the PI3K/Akt signaling pathway." (PMID 33557187, 2021). "In this study, we examined the expression of their biosynthetic enzymes, FUT1, FUT2, B3GALT5 and ST3GAL2, in 135 hepatocellular carcinoma (HCC) tissues by qRT-PCR." (PMID 28883415, 2017).
lung carcinoma (4 papers, 2021 to 2026). "In contrast, in lung cancers, including LUAD and LUSC, FUT1 expression was significantly higher in normal tissues than in tumor tissues." (PMID 40084262, 2025).
Arthritis (3 papers, 2014 to 2024). Inflammation of a joint. "We propose that fut1 plays roles in mediating arthritis by this multistep process." (PMID 24467809, 2014).
prostate carcinoma (3 papers, 2013 to 2022). A carcinoma that arises from epithelial cells of the prostate gland. "The FUT1 gene has been experimentally identified in LNCaP cells and prostate cancer tissues and associated to the H (II) epitope (Fucα1,2Galβ1–4GlcNAc)." (PMID 23326219, 2013). "Knockdown of CD44 or FUT1 genes dramatically reduced F77-induced apoptosis in prostate cancer cell lines." (PMID 29423071, 2018). "FUT1 and one of GCNT1, GCNT2 or GCNT 3 are essential enzymes for F77-specific O-linked glycosylation in prostate cancer cells." (PMID 29423071, 2018). "The FUT1 gene has been experimentally identified in LNCaP cells and prostate cancer tissues as responsible for production of the H (II) epitope." (PMID 23326219, 2013). "Downregulation of CD44 or FUT1 genes significantly reduced F77-induced apoptosis in prostate cancer cell lines, suggesting that the binding site of F77 may require fucosylation modification." (PMID 35936713, 2022).